CBX1 (chromobox 1)
Description:
Component of heterochromatin, which recognizes and binds histone H3 tails methylated at 'Lys-9', leading to epigenetic repression. Also recognizes and binds histone H1.4 methylated at 'Lys-26' (H1.4K26me). Excluded from chromatin when histone H1.4 is Simultaneously methylated at Lys-26 (H1.4K26me) and phosphorylated at Ser-27 (H1.4S27Ph). Interaction with lamin B receptor (LBR) can contribute to the association of the heterochromatin with the inner nuclear membrane (By similarity).
Synonyms: CBX; HP1Hs-beta; M31; MOD1; HP1-BETA; Hp1beta; HP1Hsbeta; p25beta
Tractability: PROTAC: UniProt records ubiquitination sites on it; ubiquitination databases record sites on it; its protein half-life has been measured; a small molecule that binds it is known.
Target class: Epigenetic regulator; Reader; Methyl-lysine/arginine binding protein; Chromodomain
Gene: Protein-coding gene on chromosome 17 (48,070,052 to 48,101,485, reverse strand). Ensembl gene ENSG00000108468.
Subcellular location: Nucleus
Subcellular location (Human Protein Atlas): Nuclear bodies; Nucleoplasm
Pathways (Reactome):
Chromatin organization: ChAHP complex assembly
Disease: HCMV Early Events
Gene Ontology:
Molecular function: enzyme binding; histone H1K26me1 reader activity; histone H1K26me2 reader activity; histone H3K9me2/3 reader activity; histone methyltransferase binding; protein binding; chromatin binding
Biological process: DNA damage response; heterochromatin formation
Cellular component: chromatin; chromosome, centromeric region; chromosome, telomeric region; heterochromatin; nuclear body; nucleoplasm; nucleus; pericentric heterochromatin; site of DNA damage; spindle
Genetic constraint (gnomAD): Loss-of-function variants: 9 observed, 21.77 expected, observed/expected ratio (o/e) 0.41, 90% interval 0.25 to 0.72. The upper end of that interval is the gene's LOEUF score, 0.72, which puts it in group 2 of 6, group 1 being the genes least tolerant of losing a copy. Missense variants: 102 observed, 219.11 expected, observed/expected ratio (o/e) 0.47, 90% interval 0.4 to 0.55. Synonymous variants: 63 observed, 79.98 expected, observed/expected ratio (o/e) 0.79, 90% interval 0.64 to 0.97.
Homologues: Orthologues: chimpanzee CBX1 (100% identical), dog CBX1 (100% identical), macaque CBX1 (100% identical), mouse Cbx1 (100% identical), pig CBX1 (100% identical), rabbit CBX1 (100% identical), guinea pig CBX1 (99% identical), rat Cbx1 (99% identical), tropical clawed frog cbx1 (91% identical), zebrafish cbx1b (84% identical), zebrafish cbx1a (80% identical), Drosophila melanogaster Su(var)205 (49% identical), and 2 more. Paralogues in human: CBX3 (70% identical), CBX5 (64% identical), CBX6 (29% identical), CBX2 (28% identical), CBX4 (27% identical), CBX8 (27% identical), CBX7 (24% identical), NPTXR (10% identical).
Diseases named in the same sentence as CBX1 in open-access papers:
CBX1 is named in the same sentence as 63 diseases in open-access papers, as found by Europe PMC text mining. Sharing a sentence is not in itself a finding about the gene and the disease. The quoted sentences say what the papers report.
breast carcinoma (17 papers, 2015 to 2022). "Initially, we used data mining techniques to determine if the expression level of HP1β/CBX1 mRNA was associated with the outcome of breast cancer patients using a published microarray dataset." (PMID 25769025, 2015). "HP1-β (CBX1) has also been associated with chemoresistance in patients with breast cancer." (PMID 34046352, 2021). "Studies indicate that CBX1 overexpression in gastric and breast cancers significantly correlates with shorter overall survival outcomes." (PMID 35969177, 2022). "Some researchers found that high expression of CBX1 was significantly related to an unfavorable progression and was correlated with chemoresistance in breast cancer." (PMID 35155439, 2022). "Therefore, these authors defined HP1-β (CBX1) as a potential target for the treatment of breast cancer." (PMID 34046352, 2021). "We found that high CBX1 and CBX3 were associated with poor survival of breast cancer patients." (PMID 33082469, 2020). "Similarly, excessive expression of CBX1 was shown to be related to poor differentiation and unfavorable prognosis of breast cancer patients." (PMID 32742466, 2020). "Recent studies have revealed that CBX1 was upregulated in HCC, castration-resistant prostate cancer and breast cancer, and a high expression of CBX1 predicted worse survival outcomes in HCC and shorter recurrence-free survival in BC patients." (PMID 36140750, 2022). "The following expression patterns were observed for breast cancer: Overexpressed, CBX1, one of 49 (1/49) analyses, CBX 2–8, 7/43, 22/53, 10/53, 2/53, 1/52, 1/41, and 6/42, respectively." (PMID 33082469, 2020). "Human HP1 proteins, HP1α/CBX5, HP1β/CBX1, and HPγ/CBX3, correlated with proliferation, invasion, and metastasis by regulating gene expression in human breast cancer cells." (PMID 33082469, 2020). "Increasing number of studies have shown that CBX1, also known as HP1-β, is overexpressed in different type of tumors, including prostate cancer (PRCA), breast cancer (BRCA), and hepatocellular carcinoma (HCC)." (PMID 33344640, 2020). "Over-expression of CBX1 had been found in castration-resistant prostate cancer (CRPC) and breast cancers (BC)." (PMID 30481161, 2018).
hepatocellular carcinoma (14 papers, 2018 to 2024). A malignant tumor that arises from hepatocytes. "Previous research indicated that high expression of CBX1 was associated with worse clinical outcomes in Hepatocellular Carcinoma." (PMID 37430195, 2023). "Noticeably higher mRNA and protein expressions of CBX1 were discovered in hepatocellular carcinoma tissues compared to normal tissues significantly linked with shorter OS." (PMID 35464847, 2022). "For example, elevated expression of CBX1/2/3/6/8 are associated with poor overall survival (OS) in hepatocellular carcinoma (HCC) patients." (PMID 34321009, 2021). "Results revealed that high expression of CBX1, CBX2, CBX3, CBX6, and CBX8 was associated with poor survival rates of hepatocellular carcinoma patients." (PMID 35677563, 2022). "Higher expression of CBX7 was correlated with better prognosis in hepatocellular carcinoma, whereas CBX1, CBX2, CBX3, CBX6 and CBX8 were identified as independent prognostic factors for poor overall survival." (PMID 35637952, 2022). "In previous studies, overexpression of CBX1 has been found in many cancers such as hepatocellular carcinoma, gastric cancer, colorectal cancer, and pituitary cancer." (PMID 34395271, 2021). "In hepatocellular carcinoma, abnormal mRNA expressions of CBX1–3, CBX6 and CBX8 were independent prognostic predictors for shorter overall survival (OS), and the mutation rate of CBX family members was up to 51%, which was also observed to be negatively associated with OS and DFS." (PMID 32894652, 2020). "In addition, high expression of CBX1 was markedly correlated with larger tumor size, poor tumor differentiation, and tumor vascular invasion in hepatocellular carcinoma." (PMID 33344640, 2020). "A previous study reported that the increased mRNA expression of HP1-β/γ (CBX1/3) and CBX2/6/8 was correlated with a worse OS, while the overexpression of CBX7 was related to a greater OS in patients with hepatocellular carcinoma." (PMID 34046352, 2021).
gastric cancer (7 papers, 2020 to 2025). A primary or metastatic malignant neoplasm involving the stomach. "High CBX1 expression was found to be significantly associated with poor prognosis in gastric cancer patients receiving adjuvant 5-fluorouracil-based chemotherapy." (PMID 34395271, 2021). "Furthermore, we noted that mRNA expression levels of CBX1/3/4/5/6/7/8 were significantly associated with gastric cancer prognosis." (PMID 35969177, 2022). "Expression levels of CBX1/2/3/4/8 in gastric cancer samples were significantly upregulated, whereas mRNA expressions of CBX7 were significantly downregulated compared to the normal control in unpaired and paired analysis." (PMID 35969177, 2022). "CBX1 has been reported to be upregulated in several cancers, such as breast, colorectal, and gastric cancer." (PMID 36292141, 2022). "Significantly upregulated mRNA expression of CBX1/2/3/4 was discovered in gastric cancer tissues compared to in normal control tissues." (PMID 35969177, 2022). "In general, mRNA expression levels of CBX1/3/4/5/6/7/8 significantly contributed to gastric cancer prognosis, confirming their potential application as biomarkers for the prediction of survival outcomes in gastric cancer patients." (PMID 35969177, 2022). "The mRNA levels of CBX1/2/3/5/8 in gastric cancer tissues were significantly upregulated." (PMID 35969177, 2022). "A prognostic gene model based on five CBX genes (CBX1, CBX2, CBX3, CBX7, and CBX8) predicted the overall survival of gastric cancer patients." (PMID 35969177, 2022). "Moreover, we found a prognostic CBXs model comprising five genes (CBX1, CBX2, CBX3, CBX7, and CBX8) for gastric cancer patients." (PMID 35969177, 2022). "In addition, the RNA-seq data revealed that the mRNA expression levels of CBX1 (HR=1.61, p = 0.02) and CBX8 (HR = 0.62, p = 0.0048) significantly correlated with clinical outcomes in gastric cancer." (PMID 35969177, 2022).
prostate carcinoma (7 papers, 2017 to 2025). A carcinoma that arises from epithelial cells of the prostate gland. "CBX1, a histone H3 Lysine 9 methyl reader and nuclear lamina protein involved in gene silencing, is heavily implicated in promoting several cancers, such as prostate cancer." (PMID 39598420, 2024). "The expression of CBX1 is elevated in prostate cancer and directly promotes the binding of the AR to the ARE." (PMID 39598420, 2024). "Biologically, CBX1 knockdown inhibited prostate cancer cell proliferation by triggering cell cycle arrest in the G1 phase, indicating that CBX1 was positively related to cancer cell proliferation." (PMID 32742466, 2020). "One study indicated that CBX1 was a key regulator in regulating cell differentiation and proliferation, and silencing CBX1 inhibited prostate cancer cell proliferation." (PMID 32742466, 2020). "In prostate cancer (PCa) tissues, higher CBX1 expression correlated with Gleason score and tri-methylation levels of histone H3K9." (PMID 30481161, 2018). "Genome-wide localization analysis reveals H3K27me3 binding at CBX1 promoter regions and thus points to heterochromatin formation corresponding to gene silencing in prostate cancer." (PMID 28403887, 2017).
cervical cancer (5 papers, 2020 to 2025). A primary or metastatic malignant neoplasm involving the cervix. "That is, CBX1 was significantly overexpressed in cervical cancer, sarcoma, lung cancer, liver cancer, GC and other cancer." (PMID 36140750, 2022). "The results showed that CBX1/2/3/5/7 are dysregulated in lung cancer and show a unified trend in cervical cancer and colorectal cancer." (PMID 34966411, 2021). "Analysis of GEO profiles (GDS2416) in 33 different biopsies from 16 cervical cancer patients showed a negative correlation between the expression of UBE2L3 and CBX3 (a gene encoding HP1γ), whereas the expression of UBE2L3 and CBX1 (a gene encoding HP1β) showed a positive correlation." (PMID 32203172, 2020).
liver cancer (5 papers, 2018 to 2023). An epithelial or non-epithelial malignant neoplasm that arises from the liver. "After mRNA expressions of CBX1/2/3/4/6/7/8 were found to be significantly associated with liver cancer patients’ prognosis, we then tried to assess the independent prognostic value of mRNA expression of CBXs in terms of OS in liver cancer patients." (PMID 30481161, 2018). "Besides, higher mRNA expressions of CBX1/2/3/6/8 were significantly associated with shorter OS in liver cancers patients, while higher mRNA expression of CBX7 was significantly related to favorable OS in liver cancer patients." (PMID 30481161, 2018). "Our results are the first to indicate the anti-tumor effect of CBX1 in ccRCC, which is contrary to its pro-tumor effect in some cancers, such as liver cancer." (PMID 34395271, 2021). "Multivariate analysis also showed that high mRNA expressions of CBX1/2/3/6/8 were independent prognostic factors for shorter OS of liver cancer patients." (PMID 30481161, 2018). "Multivariate analysis showed that high mRNA expressions of CBX1/2/3/6/8 were independent prognostic factors for shorter OS of liver cancer patients." (PMID 30481161, 2018). "In liver cancer, CBX1/2/3/6/8 were found to be a prognostic biomarker." (PMID 37430195, 2023). "Besides, higher mRNA expression of CBX1 was also significantly related with shorter OS of liver cancers patients and was an independent prognostic factor for shorter OS of liver cancer patients, indicating CBX1 took part in the tumorigenesis of HCC." (PMID 30481161, 2018).
lung carcinoma (4 papers, 2020 to 2022). "In lung cancer, the expression of CBX1, CBX2, CBX3, and CBX5 was up-regulated, while CBX7 was down-regulated." (PMID 34966411, 2021).
breast tumors (3 papers, 2017 to 2020). "Noteworthily, CBX1 and CBX2 were associated with chemoresistance whereas CBX7 was associated with tamoxifen sensitivity, as well as chemosensitivity in breast tumors." (PMID 29190923, 2017). "Similarly, over-expression of CBX1 was also found to be related with poorly differentiated breast tumors and poorer prognosis of BC patients." (PMID 30481161, 2018). "CBX1 and CBX2 might be important predictor of chemoresistance in breast tumors." (PMID 29190923, 2017).
glioblastoma (3 papers, 2022 to 2025). The most malignant astrocytic tumor (WHO grade IV). "We found that compared to differentiated glioblastoma cells (DGC), expression of CBX2, CBX3, and CBX5 were upregulated, while CBX1, CBX4, CBX6, CBX7, and CBX8 were downregulated." (PMID 39988672, 2025).
ovarian carcinoma (3 papers, 2012 to 2022). A malignant neoplasm originating from the surface ovarian epithelium. "Subsequently, the association between the mRNA expression of CBX1-3 and the survival outcome of ovarian cancer patients with diverse pathological grades was further evaluated." (PMID 32742466, 2020). "Notably, in women with ovarian cancer, increased CBX1 mRNA expression was linked to a short OS in all stages and in the grade II and grade III subgroups." (PMID 32742466, 2020). "In our research, we found that upregulation of CBX1 expression was obviously associated with worse prognosis in all patients with ovarian carcinoma, especially for those with the serous histological type, grade II, grade III, and all stages and for those treated with Taxol, platin, or Taxol+platin." (PMID 32742466, 2020). "In summary, our study reveals that CBX1-3 are prognostic candidates for predicting unfavorable clinical outcomes in ovarian cancer patients." (PMID 32742466, 2020). "The prognostic value of CBX1 in ovarian carcinoma and the expression of CBX1 at the transcriptional level and translational level in ovarian cancer tissues have not been further investigated." (PMID 32742466, 2020). "In ovarian cancer patients who were treated with Taxol, platin, and Taxol+platin chemotherapy, increased CBX1 expression was involved in poorer OS and PFS." (PMID 32742466, 2020). "High expression levels of CBX1 and CBX3 were significantly associated with chemotherapy resistance in ovarian cancer patients." (PMID 32742466, 2020). "IHC staining analysis indicated that CBX1 expression in ovarian carcinoma specimens was obviously higher than that in normal ovarian tissues." (PMID 32742466, 2020). "Collectively, higher CBX1 mRNA expression was associated with worse OS in grade II and grade III patients with ovarian cancer." (PMID 32742466, 2020). "In contrast to the analyses for CBX1-3 in all ovarian cancer patients, analyses focusing on the expression of the other 5 CBX members revealed either inconsistent or irrelevant results for both OS and PFS in all patients with ovarian malignancy." (PMID 32742466, 2020). "Taken together, our results showed that CBX1 may be a vital regulator in the carcinogenesis of ovarian cancer and acted as a promising candidate for predicting prognosis." (PMID 32742466, 2020). "Therefore, our results indicated that CBX1-3 could be attractive biomarkers for predicting poor prognosis of ovarian cancer." (PMID 32742466, 2020). "Significant down-regulation of CBX1 and CBX7 was found in ovarian cancer (OV) tissues compared to normal tissues, while the expression levels of CBX3 were significantly up-regulated in OV tissues." (PMID 35155439, 2022). "Subsequently, IHC analysis found that CBX1, CBX2 and CBX3 expression was significantly higher in ovarian cancer tissues than in the corresponding controls." (PMID 32742466, 2020). "Specifically, high expression levels of CBX1, CBX2 and CBX3 all predicted unfavorable OS and PFS in all ovarian cancer patients." (PMID 32742466, 2020). "The results revealed that highly expressed CBX1 mRNA had no significant influence on OS in ovarian cancer patients with grade I tumors." (PMID 32742466, 2020). "However, increased expression of CBX1 did not impact the PFS in all grades of ovarian carcinoma." (PMID 32742466, 2020).
sarcoma (3 papers, 2019 to 2022). A usually aggressive malignant neoplasm of the soft tissue or bone. "The expression levels of HP1-α/β/γ (CBX1/3/5) and CBX7 were associated with overall survival (OS) in patients with sarcoma, while high expression levels of CBX7 were related to disease-free survival (DFS)." (PMID 34046352, 2021). "With regard to the Barretina sarcoma database, the expression levels of HP1-β (CBX1) in pleomorphic liposarcoma showed a fold-change of 2.826 when compared with normal samples and a fold-change of 3.315 when compared with normal samples in leiomyosarcoma." (PMID 34046352, 2021). "In conclusion, our study showed that HP1-α/β/γ (CBX1/3/5) and CBX4/6/8 were highly overexpressed in human sarcoma tissues." (PMID 34046352, 2021). "According to data arising from the Oncomine database, we found that HP1-α/β/γ (CBX1/3/5) and CBX4/6/8 were all highly expressed in sarcoma." (PMID 34046352, 2021). "HP1-α/β/γ (CBX1/3/5) and CBX4/6/8 were found to be overexpressed in human sarcoma, and CBXs were upregulated in almost all the sarcoma cell line." (PMID 34046352, 2021).
diffuse gastric adenocarcinoma (2 papers, 2020 to 2022). An adenocarcinoma arising from the stomach. "In Chen's gastric dataset, CBX1 was found to be upregulated in diffuse gastric adenocarcinoma (fold − change = 1.516 and P = 2.83E − 08), gastric mixed adenocarcinoma (fold − change = 1.66 and P = 2.25E − 6), gastric intestinal-type adenocarcinoma (fold − change = 1.613 and P = 2.38E − 13)." (PMID 33344640, 2020).
diffuse large B-cell lymphoma (2 papers, 2025). "CBX1 overexpression in diffuse large B-cell lymphoma (DLBCL), has been associated with resistance to common anti-tumor drugs, suggesting a potential role in therapy resistance in leukemia." (PMID 40175347, 2025). "The results demonstrated a marked upregulation of CBX1 expression in LIHC as well as in various cancers, such as cholangiocarcinoma, diffuse large B-cell lymphoma, lung squamous cell carcinoma, pancreatic adenocarcinoma, pheochromocytoma, paraganglioma, and thymoma." (PMID 40572671, 2025).
gastric adenocarcinoma (2 papers, 2020 to 2022). "In Cho's gastric dataset, CBX1 was overexpressed in gastric adenocarcinoma (fold − change = 2.415 and P = 4.52E − 6)." (PMID 33344640, 2020).